ENSG00000274868
Gene: Miscellaneous RNA gene on chromosome 21 (8,388,898 to 8,388,987, forward strand). Ensembl gene ENSG00000274868.
Gene Ontology:
Biological process: chromatin remodeling